CRP (C-reactive protein)
Diseases named in the same sentence as CRP in open-access papers (continued):
Sharing a sentence is not in itself a finding about the gene and the disease.
Hyperglycemia (continued). "In conclusion, the results of this nationwide population-based survey showed that the combined effect of high levels of inflammation and hyperglycemia was associated with increased odds of MCI, which was true for a high level of only CRP or a high level of only HbA1c." (PMID 35252292, 2022). "The current work has implications for clinical outcome of GBS patients, demonstrating how FPG hyperglycaemia and higher CRP at hospital admission could be a bad prognostic factor for mechanical ventilation." (PMID 35677334, 2022). "Additionally, serum miR-10a, miR-21, miR-33a, miR-125a, and miR-146a levels were positively correlated with TC, TG, LDL-c, CRP, and IL-1β levels in individuals with hyperglycemia and hyperlipidemia." (PMID 36355127, 2022). "We also found that the initial and mid‐term blood glucose levels were related to markers of infection, such as CRP and the ESR, which indicates that hyperglycemia might be associated with the release of more inflammatory cytokines." (PMID 34967028, 2022). "Furthermore, they showed that with systemic inflammation (C-reactive protein), PaO2/FiO2 and hyperglycaemia, epicardial adipose tissue inflammation was significantly associated with ICU hospitalisation, invasive ventilation and death." (PMID 35807129, 2022). "Notably, treatment with metformin, insulin, or a combination of both was associated with failure to normalise glucose levels in all patients and the hyperglycaemia observed was more pronounced in patients with T2D and high CRP levels." (PMID 35844722, 2021). "We next hypothesized that part of the association of BMI with severity is mediated by high glucose levels (hyperglycaemia), CRP and LDH." (PMID 33851033, 2021). "Although the mechanism of the relationship between CRP and hyperglycaemia is not completely clear, it has been shown that higher levels of CRP are associated with diabetic polyneuropathy." (PMID 34831711, 2021). "Hyperglycemia and elevated levels of CRP were the blood parameters in visit 3 that demonstrated the greatest discriminative power to detect complications in the same visit (AUC 0.618; 95% CI 0.509–0.727; p = 0.038 and AUC 0.629; 95% CI 0.519–0.738; p = 0.024, respectively)." (PMID 33266483, 2020). "Although the mechanisms underlying the association between CRP and hyperglycemia have not been fully elucidated, there are some possible explanations." (PMID 31143476, 2019). "However, compared to changes in controls, participants in the Mediterranean diet arm had no significant changes in any of the inflammatory biomarkers or adipokines (IL-6, IL-8, CRP, and adiponectin), markers of hyperglycemia (FPG and insulin), or FMD." (PMID 30271610, 2018). "The positive relation in cross-sectional studies or case–control studies could be due to CRP being a consequence of hyperglycemia." (PMID 28178951, 2017). "Therefore, a prospective study is needed to ascertain the elevation of CRP before the onset of hyperglycaemia in the development of T2D." (PMID 28178951, 2017). "In addition, tumor necrosis factor-alpha, IL-1 beta, C-reactive protein, and other inflammatory factors can suppress the release of GnRH and LH in states of hyperglycemia." (PMID 27006953, 2016). "This may be mediated in part by CRP, which has been shown to directly decrease eNOS protein expression and activity and/or hyperglycemia that promotes eNOS glycosylation thereby reducing the active form of NO." (PMID 26346823, 2015). "Regarding the hematologic and biochemical parameters in acute stroke, hyperglycemia (blood sugar [BS] >150 mg/dl), higher serum uric acid level, C-reactive protein (CRP) level, white blood cell (WBC) count, and lower hemoglobin (Hgb) level were found to be predictors for bad outcome or death of ICH." (PMID 25781880, 2015). "Furthermore, hyperglycemia enhances inflammatory responses as reflected by increased plasma concentrations of C-reactive protein, cortisol and cytokines which, by themselves, are neurotoxic." (PMID 24941010, 2014).
Hyperglycemia (continued). "Thus, there appears to be an interaction between hyperglycemia and high hs-CRP levels beyond each factor alone in CAS development." (PMID 24204905, 2013). "Hyperglycemia can potentially promote the production of CRP." (PMID 21663637, 2011). "Indirect ophthalmoscopy disclosed signs compatible with CRAO and laboratory investigations revealed erythrocyte sedimentation rate of 74 mm/h, C-reactive protein (CRP) level of 21 mg/l, hyperglycemia, hyperuricemia, hypertriglyceridemia and hypercholesterolemia." (PMID 22737328, 2010). "Besides, Hyperglycemia promotes the secretion of pro-inflammatory cytokines including C-reactive protein (CRP), interleukin-6 (IL-6), and tumor necrosis factor-alpha (TNF-α), all of which have been shown to contribute to DKD progression and cardiovascular disease development." (PMID 40747306, 2025). "Hyperglycemia, as observed in T2D, is associated with inflammation characterized by elevated levels of proinflammatory cytokines, such as interleukin-6 (IL-6), tumor necrosis factor-alpha (TNF-α), and C-reactive protein (CRP) and these altogether increase the risk of CVD." (PMID 39683570, 2024). "In addition, hyperglycemia induces certain inflammatory factors [tumor necrosis factor-α (TNF-α), interleukin-6 (IL-6), C-reactive protein (CRP), etc.] and inflammatory reactions, all of which cause varying degrees of damage to cardiomyocytes, blood vessels, and even the heart." (PMID 37448666, 2023). "Third, stress hyperglycemia could generate reperfusion injury via oxidative stress and inflammatory process with increased expression of endothelial adhesion molecules and monomeric C-reactive protein." (PMID 36777360, 2023). "Consequently, down-stream biomarkers of inflammation that may have responded to hyperglycaemia and hyperglycaemia-induced oxidative stress, namely CRP and IL-6, were unchanged." (PMID 38231672, 2023). "Therefore, elevated CRP levels may be a consequence of hyperglycemia, instead of being an etiological biomarker in T2D development." (PMID 28178951, 2017). "Hyperglycemia activates pro-inflammatory cytokines such as IL-6 and TNF-α, which in turn stimulate hepatic CRP production and upregulate MMP-9 expression at the site of tissue injury." (PMID 40364880, 2025). "Laboratory tests revealed an elevated C-reactive protein (CRP) level of 69.7 mg/L and hyperglycemia with a blood glucose level of 391 mg/dL." (PMID 40143221, 2025). "Logistic regression models incorporating MDW, Quick Sequential Organ Failure Assessment (qSOFA) score, age, and C-reactive protein (CRP) levels were compared to the Canada Acute Coronary Syndrome (C-ACS) score and stress hyperglycemia ratio (SHR)." (PMID 40460177, 2025). "We, therefore, propose a glycemic status (normoglycemia, borderline-hyperglycmeia, hyperglycemia) prediction model by using glycemic indicators in concert with other routine clinical diagnostics (CBC and CRP)." (PMID 38212326, 2024). "It was found that higher levels of ACAG had a significant correlation to hyperglycemia, insulin, HOMA-IR, HbA1c, total cholesterol, triglycerides, CRP, urine albumin/creatinine and eGFR at baseline (all P<0.05)." (PMID 39574951, 2024). "The mature miR-199a-5p shares the seed CCAGUGU with miR-199b-5p and thus was inputted into the IPA software alongside CRP, HbA1c, VEGF-D, and hyperglycemia to imitate a diabetic state." (PMID 39125657, 2024). "In this study, we have investigated the interplay between inflammation, RBC parameters, and hyperglycemia by employing clinical diagnostics of CBC, CRP, HbA1c, and FBG (fasting blood glucose) towards developing a predictive model of glycemic outcomes." (PMID 38212326, 2024). "The patients that developed Shanghai fever were typically children with high C-reactive protein (CRP), hyponatremia, and hyperglycemia." (PMID 37325686, 2023). "Periodontal disease has been associated to the generation of proinflammatory mediators connected to hyperglycemia (IL-6, TNF-α, and CRP)." (PMID 36557312, 2022).
Hyperglycemia (continued). "Decreased insulin sensitivity and increased glucose production lead to decreased islet cell function and hyperglycemia, as well as increased release of inflammatory factors (such as IL-6, TNF-α, and C-reactive protein)." (PMID 35432188, 2022). "Hyperglycemia is also correlated with increased inflammatory markers, including tumor necrosis factor-α (TNF-α), interleukin (IL)-6 and C-reactive protein (CRP)." (PMID 35330131, 2022). "Both T2DM and new-onset hyperglycemia groups demonstrated higher levels of inflammatory markers, namely white blood cell counts (WBC), C-reactive protein (CRP), D-dimer, and interleukin-6, except for the plasma fibrinogen concentration." (PMID 35949446, 2022). "Inflammatory markers were significantly higher among patients with hyperglycemia, especially WBC, D-dimer, ALT, LDH, and CRP, than those with normoglycemic levels." (PMID 35989853, 2022). "T2DM is a low level chronic inflammatory disease, accompanied by elevated IL-6 and C-reactive protein (CPR), while chronic inflammation can build a bridge between hyperglycemia and cognitive impairment." (PMID 36310847, 2022). "Long-time hyperglycemia and aging increase production of inflammatory factors, such as IL-6, TNF-α, and CRP, which promote the onset of DPN." (PMID 31781662, 2019). "The prevalence rate of raised BP, hyperglycemia and low HDL cholesterol was higher in group with hs-CRP ≥ 1 mg/L than hs-CRP < 1 mg/L, and in hyperuricemia group than normal uric acid group." (PMID 27006878, 2016). "OSA is independently associated with increased prevalence and severity of hypertriglyceridemia and hyperglycemia, as well as with several other markers of metabolic and inflammatory dysregulation (cholesterol/HDL ratio, uric acid and C-reactive protein)." (PMID 20711453, 2010). "In this study, we aim to integratively investigate the interplay between inflammation, RBC parameters, and hyperglycemia by employing clinical diagnostics of CBC, CRP, HbA1c, and FBG (fasting blood glucose) tests towards developing a predictive model of glycemic outcomes." (PMID 38212326, 2024). "Laboratory tests indicated a white blood count (WBC) of 10,480/mL, hyperglycemia (serum glucose 350 mg/dL), impaired renal function (urea 63 mg/dL and creatinine 1.6 mg/dL, GFR 34 mL/min/1.73 m2), and elevated C-reactive protein (CRP) at 116 mg/L (normal range < 5 mg/L)." (PMID 38921266, 2024). "Hyperglycemia in DM leads to the glycation of various proteins, triggering an inflammatory milieu at the cellular and tissue levels, with increased cytokines levels such as tumour necrosis factor-alpha (TNF-α), interleukin-6, and C-reactive protein." (PMID 39553031, 2024). "All immunological biomarkers (ferritin, LDH, CRP, procalcitonin, IL-6, and CRP/ALB), coagulation biomarkers (aPTT, D-dimer, fibrinogen, PT, and INR), and hyperglycemia biomarkers (random glucose and HbA1c) were significantly higher in the severe patients compared to the other severity groups." (PMID 37448393, 2023). "Comparing patients who died with those who survived presented a significantly higher frequency of male sex, older age, hypoxemia, hypoglycemia, or hospital hyperglycemia (a hospital glucose level >140 mg/dL), AST–ALT ratio >1, elevated CRP, and altered arterial pH." (PMID 37459312, 2023). "SeNP and/or BV treatments improved the deleterious effects induced with STZ administration by improving the serum insulin concentrations, which resulted in decreasing the hyperglycemia, decreasing the serum BUN, creatinine and CRP while increasing the serum albumin concentrations." (PMID 36984840, 2023). "In conclusion, our findings imply that hyperglycaemia does not influence CRP levels in patients with CAP, although admission CRP levels were positively associated with IR." (PMID 38202252, 2023).
Hyperglycemia (continued). "Out of the nine salivary cytokines we analyzed, CRP and insulin levels strongly differentiated obese vs. non-obese youths and individuals with intermediate hyperglycemia vs. those with normal glycemia." (PMID 35757631, 2022). "The possible explanation considering the link between CRP and T2DM development may be the role of oxidative stress in inducing hyperglycemia, which further promotes inflammatory response and elevation of CRP." (PMID 35620114, 2022). "Hyperglycemia also leads to persistent inflammation, expressed by elevated levels of pro-inflammatory cytokines and inflammatory markers, e.g., tumor necrosis factor α (TNF-α) and C-reactive protein (CRP)." (PMID 36555387, 2022). "This is an intriguing point because CRP and PCT could have a double effect on mortality, both direct and indirect mediated by hyperglycemia, being key markers and predictors of this outcome." (PMID 36371199, 2022). "Patients with stress hyperglycemia had significantly higher levels of IL-10, IL-10/TNF-α ratio, CXCL10, and CRP than patients without stress hyperglycemia." (PMID 36059840, 2022). "In contrast, a study in the US Hispanic population (n = 3923, age = 18–74 years), which measured inflammation by CRP did not evidence a mediation link between chronic psychosocial stress and hyperglycaemia." (PMID 34206644, 2021). "Compared with patients with T2D without hyperglycemia, hyperglycemic patients without T2D had statistically significantly higher plasma CRP and serum LDH (both p < 0.05)." (PMID 34206813, 2021). "Moreover, inflammatory markers and mediators such as c-reactive protein (CRP), interleukin-6 (IL-6) and TNF-α are present in systemic inflammation induced by hyperglycemia." (PMID 32932898, 2020). "Patients with hyperglycemia, i.e. BSL ≥ 11.1 mmol/L, had higher levels of C-reactive protein (CRP), white blood cell count (WBC), creatinine kinase (CK), higher heart rates and lower left ventricular ejection fraction (LVEF) and increased N-terminal pro-brain natriuretic peptide." (PMID 31672144, 2019). "He had recurrent episodes of hypoglycemia, hyperglycemia, metabolic acidosis, abdominal distension, leukocytosis, increase in C-reactive protein levels, with negative blood cultures and suspected inborn error of metabolism." (PMID 26838603, 2016). "Like CRP, AGEs–RAGE system stimulated by hyperglycemia could be responsible for the deterioration of cognition through an immune inflammatory pathway." (PMID 26578953, 2015). "Neither C-reactive protein nor the extent of myocardial damage was found to be related to hyperglycemia in ACS patients." (PMID 23270530, 2012). "ROC curve analysis showed that NHR and CRP had comparable performance when assessed using HbA1c, whereas NHR demonstrated superior ability to distinguish hyperglycemia in the FBG context, suggesting that NHR may capture both short and long-term metabolic-inflammatory changes." (PMID 41373239, 2025). "After correction for patients’ age and the number of comorbidities (OR = 0.891; p = 0.009) and even after additional correction for initial CRP, HbA1c, and stress hyperglycaemia, HDL still proved to be a significant negative predictor for intrahospital mortality." (PMID 39685701, 2024). "Additionally, CRP levels did not impact blood glucose concentration or the occurrence of hyperglycemia." (PMID 39215344, 2024). "We conclude that CRP > 5 is a risk factor associated with the occurrence of respiratory failure in GBS patients and may predict worse GBS prognosis; however, FPG hyperglycaemia alone measured at admission is not connected with respiratory failure." (PMID 35677334, 2022). "Correlations with measures of hyperglycemia, adiposity, lipids, blood pressure and inflammation were generally weaker, exceptions being FABP4 and ADM which correlated with body fat content (r = 0.75 and r = 0.69, respectively), and IL6 which correlated with CRP (r = 0.63) and WBC (r = 0.62)." (PMID 33279861, 2021).
Hyperglycemia (continued). "More than half of the survivors had an increased CRP level, and less than 30% of the survivors had abnormal blood biochemistry findings involving hyperglycemia, liver function, and myocardial enzymes, rather than abnormal renal function and coagulation function in the 72 survivors." (PMID 33983981, 2021). "Hyperglycemia can induce nonenzymatic protein glycation, and the resulting advanced glycation end products (AGEs) have been shown to stimulate macrophages, causing them to release cytokines such as IL-6 and TNF-α, as well as C-reactive protein." (PMID 34068221, 2021). "In addition, hyperglycaemia may be a trigger to inflammatory response in T1DM, because it may increase the levels of circulating C-reactive protein (CRP), free fatty acids, CXCL-8, and pro-inflammatory cytokines, such as IL-6, IL-1β and TNF-α." (PMID 28202039, 2017). "However, the levels of CRP (72.7 mg/L vs. 57.9 mg/L), D-dimer (1540 ng/mL vs. 1139 ng/mL), AST/ALT ratio (1.5 vs. 1.2), and the proportion of patients requiring invasive mechanical ventilation (30.8% vs. 23.3%) on admission were higher in the new-onset than in the T2DM hyperglycemia group." (PMID 35949446, 2022). "Therefore, elevated CRP levels might be by-products of hyperglycemia, rather than directly contributing to the development of incident T2D." (PMID 28178951, 2017). "Plasma CRP and serum LDH were statistically significantly higher in patients with hyperglycemia among both patients with and without T2D (all p < 0.01)." (PMID 34206813, 2021). "Neither hyperglycaemia or supplementary Cr(III) complexes had significant influence on serum GST, TBARS and CRP levels." (PMID 30826908, 2020). "Thus, the CRP level may not be reduced until hyperglycemia is controlled." (PMID 28912573, 2017). "Additionally, hyperglycemic patients with T2D had statistically significantly plasma CRP and serum LDH than patients without T2D who did not have hyperglycemia (both p < 0.001)." (PMID 34206813, 2021).